Y_RNA (Y RNA )
Gene: Miscellaneous RNA gene on chromosome 3 (37,093,133 to 37,093,234, reverse strand). Ensembl gene ENSG00000206645.
Homologues: Orthologues: chimpanzee Y_RNA (100% identical), macaque Y_RNA (95% identical). Paralogues in human: Y_RNA (87% identical), RNY3 (86% identical), Y_RNA (86% identical), RNY3P1 (85% identical), RNY3P14 (85% identical), Y_RNA (85% identical), Y_RNA (84% identical), RNY3P16 (83% identical), Y_RNA (83% identical), RNY3P11 (82% identical), RNY3P5 (82% identical), RNY3P7 (82% identical), and 93 more.